TNF (tumor necrosis factor)
Diseases named in the same sentence as TNF in open-access papers (continued):
Sharing a sentence is not in itself a finding about the gene and the disease.
pancreatic cancer (continued). "Among those factors, only TNF-α reduced the expression of BGLAP in pancreatic cancer cell lines." (PMID 18163903, 2007). "Additionally, the roles of TNF-α in pancreatic cancer have been documented." (PMID 41488204, 2026). "In the case of advanced lesions, pro‐inflammatory cytokines like L‐1beta, IL‐5, IL‐6, IL‐8 and TNF‐alpha were elevated in high‐grade dysplasia/pancreatic cancer compared to low‐grade/moderate dysplasia group, suggesting that immune response patterns may change across the natural history of disease." (PMID 39482824, 2025). "Pancreatic tumors are notoriously difficult to inject in ultrasound guidance, and the TNFerade approach required not only the virus to reach tumor cells, but also the subsequent radiotherapy needed to hit the same cells to activate the promoter driving TNFα expression." (PMID 38546220, 2024). "However, high PD1 expression leads to CD8 + T cell exhaustion, and an increase in PD1 + CD8 + T cells and a decrease in TNFα + /IFNγ + CD8 + T cells due to ABHD17C in the pancreatic cancer microenvironment can promote the immune escape of tumor cells and inhibit immune killing." (PMID 37273016, 2023). "Thus, we hypothesized that alizarin can also inhibit pancreatic cancer cells by affecting TNF-α-mediated TAK1-NF-κB signaling cascades." (PMID 35541911, 2022). "The role of TNF in EMT and the direct effect of monocytes on the motility of pancreatic cancer cells was then investigated, revealing a phenotypic transition that was attenuated when cancer cells and monocytes were co-cultured in the presence of inhibitors of TNF production and anti-TNF antibodies." (PMID 35873564, 2022). "TNF-α 308G/A (rs1800629) gene polymorphism was a significant predictor for cachexia in both the lung and pancreatic cancer patients rather than that of TNF-α 1031T/C (rs1799964) gene, which was associated with lower risk of cachexia in the NSCL cancer patients." (PMID 34900737, 2021). "Furthermore, the authors showed that mesothelin induced an NFκB/Akt-dependent anti-apoptotic pathway that can protect pancreatic cancer cells from TNF-α-induced apoptosis, and this was a probable mechanism of pancreatic cancer cell survival in midst of inflammation and inflammatory mediators." (PMID 33637083, 2021). "Hence, the suppression of TAMs and the modulation of TNFα dependent pathways could offer new perspectives in immunotherapies of pancreatic cancer patients especially with remaining vital tumor cells and lost vagal modulation." (PMID 28160574, 2017). "However, it is also reported that pancreatic tumor secreting TNFα may be the crucial trigger of tumor recurrence and metastasis after surgical resection." (PMID 20367887, 2010). "Therefore, MA together with TNFα could be new promising agents in the treatment of pancreatic cancer." (PMID 20367887, 2010). "Therefore, our results demonstrated that combination of MA with TNFα could significantly affect pancreatic cancer cell viability and induce cancer cell apoptosis." (PMID 20367887, 2010). "Compound 17 (quercetin-3-methyl ether) interacted with multiple key targets related to pancreatic cancer, including AKT1, EGFR, TNF, CASP3, and SRC, and occupies a central position within the PPI network, indicating the potential regulatory interaction." (PMID 41006588, 2025). "Pancreatic tumors specifically feature three targets: pancreatic and duodenal homeobox 1 (PDX1), KRAS protooncogene GTPase (KRAS), and tumor necrosis factor (TNF)." (PMID 41041638, 2025). "Our previous work used oral cancer, pancreatic cancer, and glioblastoma to demonstrate that the supernatant of IL-2 and anti-CD16 antibody-treated NK cells, as well as IFN-γ and TNF-α, mediate the differentiation of cancer stem-like tumors." (PMID 39851518, 2025). "In pancreatic cancer, CAFs have been found to secrete thymic stromal lymphopoietin (TSLP) following activation by tumor-derived TNF-α and IL-1β." (PMID 40453074, 2025).
pancreatic cancer (continued). "Expression of IL33 and other IRF3 target genes, TNF, IL1B, and CXCL10, were highly upregulated in pancreatic cancer compared to the normal pancreas in a large collection of samples represented in TCGA and GTEx databases." (PMID 38816352, 2024). "Another study reports that TNF-α, which is abundantly present in PDAC, induces EndMT and acts at least partially through TIE1 regulation in murine pancreatic tumors." (PMID 38608280, 2024). "Oncolytic adenoviruses (OAds) expressing TNF-α and IL-2 was able to induce CAR-dependent and CAR-independent host immunity and alter the immunosuppressive TME in pancreatic cancer." (PMID 39633491, 2024). "We showed that VISTA significantly reduces the TNFα and IFNγ expression of CD4+ or CD8+ T cells cocultured with pancreatic tumor cells." (PMID 37190254, 2023). "It is believed that NK cells induce the differentiation of pancreatic cancer stem cells by secreting IFN-γ and tumor necrosis factor -α, reshaping the tumor microenvironment and inhibiting tumor proliferation." (PMID 38012210, 2023). "By modulation of death receptor 3, a receptor for tumor necrosis factor (TNF), fisetin induces apoptosis, inhibits proliferation, and inhibits invasion in chemoresistant pancreatic cancer cells." (PMID 37371804, 2023). "Robinin (1 μM/ml) largely attenuated IL-6 and TNF-α expression in Mia-PACA2 and PANC-1, which certified that Robinin can obviously inhibit the inflammation in pancreatic cancer." (PMID 38110966, 2023). "The findings of this study indicate that VRK2 promotes the progression of pancreatic cancer by activating the TNFα/NF-κB signaling pathway, suggesting that VRK2 is a potential therapeutic target for pancreatic cancer." (PMID 35173553, 2022). "In a pancreatic cancer cell line based testing checked the effect of 5-fluorouracil (5-FU), Irinotecan (CPT-11), Methotrexate (MTX), or a cytokine (tumor necrosis factor-α (TNF-α)) in combination with HSV-1." (PMID 35686109, 2022). "The inflammatory cytokines TNF-α and LIF influence the CXCL-8 expression in pancreatic cancer progression." (PMID 35887223, 2022). "Of note, pancreatic carcinoma cells constitutively express LIF and its heterodimer receptor (LIFR and gp130), and TNFα, IL1β or LIF itself enhanced the expression of LIF mRNA." (PMID 35565186, 2022). "In the cytokine signaling pathway, PER1 expression is suppressed by tumor necrosis factor (TNF)-α, and knockdown of PER1 decreases the proliferation of pancreatic carcinoma cells." (PMID 36385012, 2022). "Although our data did not demonstrate significant differences in cytokine levels, except for IL-8 and TNF-α, a similar trend in the data suggests that immunological effects are induced by IORT in pancreatic cancer." (PMID 34641806, 2021). "S100A8/A9 secreted by monocytes can induce pancreatic tumor cells to secrete proinflammatory cytokines, including IL-8, fibroblast growth factor (FGF), and tumor necrosis factor-alpha (TNF-α), mediated in part by RAGE in pancreatic tumor cells." (PMID 34527585, 2021). "The CD95L-antagonist sCD95Fc substantially reduced cytokine (TNF-α or TRAIL)-stimulated IL-6 and IL-8 expression and generally lowered the pro-inflammatory status of pancreatic cancer cells as well as their stem cell properties." (PMID 34771621, 2021). "There are drugs used in pancreatic cancer-induced cachexia that inhibit cytokines such as e.g., TGF-β, TNF-α and IL-6." (PMID 33557173, 2021). "Co-culturing NK cells with immunosuppressive pancreatic cancer-derived EVs expressing TGF-β1 resulted in the significant downregulation of NKG2D, CD107a, TNF-α, and INF-γ in NK cells, reducing their cytotoxicity against pancreatic tumors." (PMID 33317058, 2020). "Upon analysis of the patients' TILs, it was found that CD56brightCD16− NK cells were the major components responsible for killing pancreatic tumor targets, as well as for secretion of IFN-γ and TNF-α." (PMID 31024520, 2019).
pancreatic cancer (continued). "Specifically, NM inhibits oxaliplatin-induced and TNF-α- and gemcitabine-induce c-IAP1/2 activity in pancreatic cancer." (PMID 31552177, 2019). "It was recently demonstrated that the close association between the master inflammatory NF-κB signaling and TNFα regulates the delicate balance between TAM and pancreatic cancer cells during the early stages of carcinogenesis." (PMID 30764482, 2019). "Signaling pathways, such as Notch, tumor necrosis factor alpha (TNFα), transforming growth factor beta (TGF-β), and hypoxia-inducible factor-1 alpha (HIF1α), are involved in the induction of EMT in pancreatic cancer cells." (PMID 31514451, 2019). "The TNFα expression levels in human pancreatic cancer tissue was not correlated with tumor stage, but it was found to be associated with chemoresistance and to be of prognostic significance, a shorter survival being correlated with higher TNFα expression levels." (PMID 30764482, 2019). "A preclinical study indicated that AEG35156 enhanced the sensitization of tumor necrosis factor (TNF)-related, apoptosis-inducing, ligand-mediated apoptosis in pancreatic carcinoma cells (Panc1)." (PMID 31284594, 2019). "Stimulation of cultured pancreatic cancer cells with S100A8 and S100A9 increased the secretion of the pro-inflammatory cytokines IL-8, TNF-α, and FGF." (PMID 30558665, 2018). "Most pancreatic cancers display overexpression of key mediators of tumor angiogenesis, including the vascular endothelial growth factor (VEGF), tumor necrosis factor -α (TNF-α) and placental growth factor (PlGF)." (PMID 29069789, 2017). "Conversely, Reg3g treatment of orthotopic pancreatic tumor mice decreased levels of Th1 cytokines such as IFN-γ, IL-12, and TNF-α." (PMID 28880262, 2017). "Of note, the proinflammatory cytokine TNFα, which we found to be secreted preferentially by Mob-MDM, was previously reported to inhibit the proliferation of various pancreatic cancer cell lines in vitro." (PMID 29046677, 2017). "IL-6 and IL-10 were significantly increased in both the HCC and GBC groups, IL-2, IL-6, IL-10, and TNF-α in the cholangiocellular carcinoma group, and IL-2, IL-6, IL-8, and TNF-α in the pancreatic cancer group." (PMID 29410961, 2017). "Consistent with the repressed angiogenetic potency, FH535 also significantly decreased the levels of pancreatic cancer cell–secreted pro-angiogenic VEGF, interleukin (IL)-6, IL-8, and tumor necrosis factor (TNF)-α." (PMID 27323403, 2016). "To identify the targeting values of TNF-α in PDAC, we measured TNF-α expression in different stages of PDAC initiation and evaluated its prognostic significance in a pancreatic cancer cohort." (PMID 27835602, 2016). "After pretreated with TNF-α and IFN-γ, the supernatant culture medium of MSCs was co-cultured with pancreatic cancer cells." (PMID 27191496, 2016). "The expression of cIAP1 inhibited AZD5582-induced cell death and TNFα production, indicating that AZD5582 targets cIAP1 in human pancreatic cancer cells." (PMID 26314849, 2015). "As demonstrated with several pancreatic cancer cell lines, CBL0137 inhibits NF-κB reporter activity induced by TNF and blocks expression of the endogenous NF-κB targets, IL-8 and TNF, including that which is induced by gemcitabine treatment." (PMID 25402820, 2014). "Interactions with ECM components have been reported to alter TNF-alpha induced changes in endothelial permeability, and the ECM proteoglycan decorin can inhibit growth of pancreatic carcinoma cells." (PMID 18460215, 2008). "The down-regulation of BGLAP by TNF-α in pancreatic cancer cells indicates that BGLAP is one of the TNF-α targets and indirectly suggests a tumor-promoting function of BGLAP in pancreatic cancer." (PMID 18163903, 2007). "Aspc-1, Capan-1, Panc-1 and T3M4 pancreatic cancer cells were treated with recombinant TGF-β1, BMP2, FGF2, Shh, Ihh and TNF-α for 48 h." (PMID 18163903, 2007).
pancreatic cancer (continued). "Further, pancreatic cancer cells lacking Ccn1 are sensitive to TNFα‐induced cell death and show inhibited polarization from M1 to M2 macrophages." (PMID 40287974, 2025). "For instance, pancreatic cancer (PC) cells secrete PGE2 and tumor necrosis factor (TNF) to attract macrophages; once infiltrated, the macrophages provoke inflammatory reactions in neighboring cancer cells, further amplifying PGE2 and TNF production via IL-1β signaling and attracting more TAMs." (PMID 41417432, 2025). "Similarly, in pancreatic cancer, CAFs facilitate a shift toward a Th2 immune response through the secretion of TSLP in response to TNF-α and IL-1β, which polarizes DCs toward an immunosuppressive phenotype." (PMID 40453074, 2025). "Upon treatment with CalebinA (10 μM), NF-κB activity was significantly suppressed in all pancreatic cancer cell lines, regardless of the presence or absence of TNF-α." (PMID 40871669, 2025). "Legendplex assays used to analyze cytokine secretion into culture supernatants of PBMC and pancreatic cancer cell lines demonstrated a significant increase in the release of both IFN-γ and TNF after treatment with B7-H3-SDIE, whereas the isotype control again had no relevant effect." (PMID 38322253, 2024). "Despite this, TNF blockade with etanercept, a soluble fusion protein containing the TNF-binding domain of TNFR2, did not significantly enhance the efficacy of gemcitabine as a single agent in patients with advanced pancreatic cancer." (PMID 39178856, 2024). "It has been shown that the combination of etanercept (an inhibitor of TNF-α) and gemcitabine failed to enhance gemcitabine efficacy in advanced pancreatic cancer." (PMID 37686338, 2023). "Additionally, CTNNB1 had the highest deep deletion rate across pan-cancer at 5%, followed by TGFB1 at 3.6% in head and neck cancer and 2.2% in non-small cell lung cancer, and TNF and PPARG in pancreatic cancer with rates of 3.6% and 1.3%, respectively." (PMID 37033970, 2023). "The researchers found that the combination of BV6 and 2′3′-cGAMP effectively triggered necroptosis in pancreatic cancer through MLKL phosphorylation and the stimulation of NF-κB, type I interferons (IFNs), TNFα, and IFN-regulatory factor 1 (IRF1) signaling pathways." (PMID 37893166, 2023). "We supplemented Etanercept and Dacomitinib to DDIT4-AS1-overexpression-BxPC-3 cells and found that the TNF or ErbB signaling pathway did not have obvious effects on the stemness of pancreatic cancer cells." (PMID 36056355, 2022). "We show that TNF-α, abundantly present in PDAC, induces EndMT, acts, at least partially, through TIE1 regulation and participates in the CAF generation process in murine pancreatic tumours." (PMID 34172716, 2021). "An early study found a negative correlation between serum TNF-α levels and body weight and body mass index in pancreatic cancer patients." (PMID 33925872, 2021). "EVs from primary pancreatic cancer cells or highly metastatic pancreatic cancer cell lines that were cocultured with NK cells lowered the cytotoxic potential and downregulated NKG2D, CD107a, TNF-α and INF-γ in NK cells." (PMID 33806053, 2021). "These cytokines, such as interleukin-1β (IL-1β), IL-6, IL-8, IL-10, tumor necrosis factor-α (TNF-α), and transforming growth factor-β (TGF-β) are potential prognostic biomarkers as well as targets in the pathogenesis of pancreatic cancer and in peripheral nerve injury." (PMID 32174830, 2020).
pancreatic cancer (continued). "As demonstrated in pancreatic cancer cells upon binding of GW501516, PPARβ/δ decreased TNFα (Tumor Necrosis Factor α)-induced NFκB activity leading to the induction of anti-inflammatory genes and consequently to the inhibition of pro-inflammatory genes through the dissociation of BCL6." (PMID 32519230, 2020). "Recent work further showed elevated IL-8 in cachectic versus non-cachectic resected and locally advanced pancreatic cancer patients, which was not the case for IL-6, IL-1β, or TNF-α." (PMID 31769424, 2019). "Moreover, several critical inflammatory cytokines including TNFα, IFN-γ, IL-1α, and IL-6 were markedly increased within DMXAA-treated pancreatic tumors compared to control tumors." (PMID 31036082, 2019). "In pancreatic cancer, CLDN1 can lead to TNF-alpha-dependent proliferation." (PMID 30519576, 2018). "It was reported that miR-203 was present in pancreatic cancer cell derived exosomes, and miR-203 suppressed the expression of toll-like receptor 4 (TLR4) resulting in the decreased levels of tumor necrosis factor-α (TNF-α) and interleukin-12 (IL-12) in pancreatic cancer cell line Panc-1." (PMID 30046565, 2018). "In pancreatic cancer cells, SIRT6-mediated increase of migration activity was mediated by Ca2+, and SIRT6 increased the expression of pro-inflammatory cytokines such as IL8 and TNF." (PMID 30524965, 2018). "In pancreatic cancer, MDSCs are known to be induced by pro-inflammatory cytokines such as interleukins, granulocyte-macrophage colony-stimulating factor (GM-CSF), interferon gamma (IFN-γ), and tumor necrosis factor (TNF)." (PMID 27322081, 2016). "Consistent with a requirement for TNFα, AZD5582-induced cell death was dramatically inhibited after exposure to TNFα-blocking antibodies, suggesting that TNFα production elicited by AZD5582 can induce apoptotic cell death in human pancreatic cancer cells." (PMID 26314849, 2015). "In the present study, we showed that QYHJ reduced TAM infiltration and effectively inhibited multiple pro-inflammatory cytokines such as TNF-α and IL-6, which suggested that QYHJ could inhibit cancer-related inflammation in pancreatic cancer." (PMID 23922983, 2013). "Moreover, G1 arrest has been attributed to endogenous NO following activation by TNF-α, IFN-γ and IL-1 in breast and pancreatic carcinoma cells." (PMID 23964349, 2013). "However, a recent phase I/II study evaluated the efficacy and tolerability of gemcitabine and etanercept, a TNF-α blocker, in 38 patients with advanced pancreatic cancer, but there was no significant improvement in survival." (PMID 39195299, 2024). "In a comprehensive study that tested levels of 25 circulating factors such as TNF-α, IFN-γ, IL-1β, and IL-6 in cachectic and weight stable patients, monocyte chemoattractant protein-1 (MCP-1) was the only biomarker significantly increased in cachectic patients with pancreatic cancer." (PMID 33925872, 2021). "Upon treatment with miR-203-positive exosomes derived from pancreatic cancer cells, dendritic cells (DCs) downregulate toll-like receptor 4 (TLR4), tumor necrosis factor-α (TNF-α), and interleukin-12 (IL-12) expression, which may prevent DC antigen presentation." (PMID 30699928, 2019). "Therefore, although safe, TNFα and anti-TNFα therapy, provide no clinical benefit in terms of the duration of survival of patients with unresectable pancreatic cancer." (PMID 30764482, 2019). "Since TNF-α and IL-12 both play critical roles in maturation of immune cells, enhancing antigen presentation of APCs, and augmenting cell immunity, miR-203 may modulate TLR-mediated immune response and facilitate immune escape of pancreatic cancer cells." (PMID 30046565, 2018). "Moreover, the Milliplex assay showed that FH535 significantly decreased VEGF, IL-6, IL-8, and TNF-α levels in culture medium, indicating that the WNT/β-catenin pathway–targeting strategy represses angiogenesis in pancreatic cancer through a mechanism involving multiple genes." (PMID 27323403, 2016).